RNU6-396P (RNA, U6 small nuclear 396, pseudogene)
Gene: Small nuclear RNA gene on chromosome 21 (46,525,618 to 46,525,722, forward strand). Ensembl gene ENSG00000202239.
Homologues: Orthologues: chimpanzee U6 (99% identical), macaque U6 (92% identical), rabbit U6 (79% identical), guinea pig U6 (74% identical). Paralogues in human: RNU6-268P (87% identical), RNU6-536P (87% identical), RNU6-140P (85% identical), RNU6-652P (85% identical), RNU6-820P (85% identical), RNU6-854P (85% identical), RNU6-1032P (84% identical), RNU6-11P (84% identical), RNU6-137P (84% identical), RNU6-19P (84% identical), RNU6-24P (84% identical), RNU6-37P (84% identical), and 1286 more.